PAGE2 (PAGE family member 2)
Synonyms: PAGE-2; GAGEC2; GAGEE2; MGC62094; CT16.4
Tractability: PROTAC: ubiquitination databases record sites on it.
Gene: Protein-coding gene on chromosome X (55,089,018 to 55,092,842, forward strand). Ensembl gene ENSG00000234068.
Gene Ontology:
Molecular function: protein binding
Homologues: Orthologues: macaque PAGE2B (86% identical), pig PAGE2B (47% identical). Paralogues in human: PAGE2B (94% identical), PAGE5 (82% identical), PAGE3 (40% identical), PAGE4 (38% identical), XAGE3 (36% identical), XAGE5 (35% identical), PAGE1 (32% identical), XAGE2 (32% identical), GAGE10 (31% identical), GAGE13 (29% identical), GAGE1 (28% identical), GAGE12C (28% identical), and 10 more.
Diseases named in the same sentence as PAGE2 in open-access papers:
PAGE2 is named in the same sentence as 8 diseases in open-access papers, as found by Europe PMC text mining. Sharing a sentence is not in itself a finding about the gene and the disease. The quoted sentences say what the papers report.
colorectal cancer (2 papers, 2014 to 2024). A primary or metastatic malignant neoplasm that affects the colon or rectum. "To elucidate such mechanisms we chose to study the Caco-2 colorectal cancer cell line during the course of its spontaneous differentiation in vitro, as we found CT genes, in particular PAGE2, -2B and SPANX-B, to be up-regulated during this process." (PMID 25229454, 2014). "Within the top five genes based on WRF (Ensemble 1 and Ensemble 2), SLC30A3, MOS, C1ORF61, and MBL1P genes were found to have an association with CRC, gene PAGE2, a gene from cancer-germline genes, was found to be upregulated in Caco-2 colorectal cancer cell line." (PMID 39897528, 2024). "In this line, we predict future studies will reveal distinct drug sensitivity profiles for colorectal cancer subtypes as possibly defined by PAGE2 and SPANX-B expression, for which the Caco-2 SD model could be used." (PMID 25229454, 2014). "To determine if this occurred in parallel to the up-regulation of PAGE2 and SPANX-B, we analyzed the GSE1614 dataset for the expression of genes representing EMT in colorectal cancer, and selected 6 genes to be validated in our model." (PMID 25229454, 2014).
psychosis (2 papers, 2017 to 2021). "In conclusion, we found that a subgroup of patients with first-episode psychosis was seropositive to the N-terminal portion of the PAGE protein family (PAGE2B/PAGE2/PAGE5), and that such seropositivity was associated with the development of schizophrenia." (PMID 28742074, 2017). "Among the three types of autoantibodies with a significantly different distribution pattern in patients versus controls, autoantibodies toward the N-terminal portion of the PAGE protein family (PAGE2B/PAGE2/PAGE5) were exclusively seen in patients with first-episode psychosis." (PMID 28742074, 2017). "Additional studies are necessary to confirm these findings and to elucidate whether PAGE2B, PAGE2, PAGE5 or another protein cross-reactive to the N-terminal end of PAGE2B is the critical autoantibody target, and to further disentangle its role in the etiopathology of psychosis." (PMID 28742074, 2017).
breast carcinoma (1 paper, 2016). "Our discovery that PAGE-2/2B was expressed in the SUM159T cells suggested that PAGE-2/2B may function in breast cancer as well." (PMID 26895102, 2016).
Psychotic episodes (1 paper, 2019). Periods of time during which an individual experiences significant disturbances in their thoughts, perceptions, emotions, and behavior, resulting in a loss of touch with reality. "PAGE2 gene encodes for a P antigen protein that was studied as possible target in psychotic episodes." (PMID 31487916, 2019).
squamous cell carcinoma (1 paper, 2019). A carcinoma arising from squamous epithelial cells. "Overexpression of CFBF, PAGE2, CALM3, DSG3, CTAG2, and FAM83C was seen only in squamous cell carcinoma." (PMID 31877723, 2019).
cancer (6 papers, 2014 to 2024). A tumor composed of atypical neoplastic, often pleomorphic cells that invade other tissues. "Notably, LIHC, KIRC, and OV cancers had the 40 same upregulated genes, such as FOXJ1, LOC100128674, MAGEC1, and PAGE2." (PMID 35813444, 2022).
tumor (2 papers, 2016 to 2023). "Thus, our discovery that SPANX-A/C/D, CTAG2, PAGE-2/2B can be necessary for invasion reveals a mechanistic contribution for these CTAs during tumor progression." (PMID 26895102, 2016).
PAGE2 also shares sentences with these, for which no sentence is quoted: schizophrenia (1 paper).